HULC (hepatocellular carcinoma up-regulated long non-coding RNA)
Diseases named in the same sentence as HULC in open-access papers (continued):
Sharing a sentence is not in itself a finding about the gene and the disease.
osteosarcoma (continued). "Therefore, we investigated the interaction of HULC and PTEN in promoting osteosarcoma cell proliferation and migration." (PMID 36213832, 2022). "Also, HULC induces the progression of osteosarcoma by regulating the miR-372-3p/HMGB1 signaling axis, and HULC accelerates the growth of human liver CSCs via autophagy." (PMID 33425489, 2021). "Among the altered lncRNA profiles, 7 lncRNAs involved TUG1, 91H, HULC, BANCR, FGFR3-AS1, HOTTIP and OMRUL, were notably increased in patients with osteosarcoma and strongly correlated to worse clinical outcomes, indicating that such lncRNAs may play oncogenic roles in maintaining tumor progression." (PMID 28415638, 2017). "However, the mechanism of HULC involved in the progression of osteosarcoma is unknown, and the interaction of HULC and PTEN has not been proved in osteosarcoma." (PMID 36213832, 2022).
pancreatic cancer (12 papers, 2015 to 2025). "HULC is also a cancer-associated lncRNA that regulates proliferation, migration, viability, and invasion in pancreatic cancer." (PMID 38559560, 2024). "Several lncRNAs, including lncRNA-UFC1, RP11-263F15.1, ABHD11-AS1, LINC00675, HULC, and C9orf139, have been shown to have the potential to be included in diagnostic approaches for pancreatic cancer." (PMID 34827663, 2021). "Higher expression of HULC is associated with poor prognosis in patients with pancreatic cancer." (PMID 38559560, 2024). "RUNX1-IT1, ENSG00000254041.1, MALAT1, LOC285194, LncRNA-UFC1, RP11-263F15.1, BC008363, MEG3, and HULC are among lncRNAs whose expressions have been correlated with the survival of patients with pancreatic cancer." (PMID 34827663, 2021). "Also, HULC is highly expressed in advanced pancreatic tumors." (PMID 38559560, 2024).
glioma (9 papers, 2016 to 2023). A benign or malignant brain and spinal cord tumor that arises from glial cells (astrocytes, oligodendrocytes, ependymal cells). "HULC silencing suppressed glioma cell proliferation and invasion, which were reversed after ESM1 overexpression." (PMID 36522312, 2022). "Our study provides insight into this mechanism by identifying the potential targets of HULC in glioma cells." (PMID 34131250, 2021). "HULC silencing suppressed angiogenesis by regulating ESM-1 via the PI3K/Akt/mTOR signaling pathway in human gliomas." (PMID 32010942, 2020). "HULC silencing suppresses angiogenesis by inhibiting the PI3K/AKT/mTOR signaling pathway in human gliomas." (PMID 28993733, 2017). "Accordingly, we further investigated the role of HULC in angiogenesis in a hypoxic environment in glioma cells through treatment with 100 μM CoCl2 for 24 h to induce a hypoxic environment." (PMID 26894862, 2016). "Silencing HULC suppressed angiogenesis by inhibiting glioma cells proliferation and invasion." (PMID 30677230, 2019). "Additionally, we found that HULC silencing could suppress the expression of ESM-1 in the glioma U87MG and U251 cell lines." (PMID 26894862, 2016).
colon cancer (7 papers, 2013 to 2024). "At the same time, studies have shown that HULC is overexpressed in colon cancer liver metastases and can be detected in blood, which can be used as a molecular marker for predicting liver metastasis of colon cancer." (PMID 32826862, 2020).
prostate carcinoma (7 papers, 2015 to 2024). A carcinoma that arises from epithelial cells of the prostate gland. "For example, in prostate cancer, lncRNA HULC was up-regulated in cancer tissues and associated with a poor overall survival of prostate cancer patients." (PMID 31479417, 2019). "Overexpression of HULC enhances prostate cancer metastasis via EMT induction and is correlated with poor prognosis." (PMID 35317831, 2022). "Silencing HULC triggers autophagy and sensitizes prostate cancer cells to irradiation-mediated apoptosis." (PMID 35317831, 2022). "It has been reported that silencing HULC promotes sensitivity of prostate cancer cells to radiotherapy and induces apoptosis and cell cycle arrest (G0/G1 phase)." (PMID 35317831, 2022). "The HULC silencing can reduce survival rate and enhance apoptosis in prostate cancer." (PMID 39512820, 2024). "Interestingly, currently performed experiments revealed the role of HULC as a tumor-promoting factor in prostate cancer." (PMID 35317831, 2022). "In this study, the transcriptional expression levels of three lncRNAs namely colon cancer associated transcript 2 (CCAT2), HULC, and FOXCUT, and the effect of NaBu on cell cycle control, apoptosis, and expressions of these lncRNAs were evaluated in two prostate cancer cell lines, PC-3 and LNCAP." (PMID 35178357, 2021). "For example, lncRNA HULC and RHPN1-AS1 have been shown to regulate autophagy and influence therapy resistance in prostate cancer through their interactions with mTOR and EGFR signaling, respectively." (PMID 39512820, 2024). "In this study, we investigated the effect of NaBu on the expressions of FOXCUT, HULC, and CCAT2 lncRNAs in two prostate cancers; PC-3 and LNCAP cell lines." (PMID 35178357, 2021).
Sepsis (6 papers, 2019 to 2023). Sepsis is defined as life-threatening organ dysfunction caused by a dysregulated host response to infection. "This lncRNA has a role in regulation of immune response, since up-regulation of HULC has been shown to has a necessary role in pro-inflammatory responses in the course of LPS-associated sepsis." (PMID 34868009, 2021). "HULC knockdown has been shown to reverse LPS-induced sepsis via the regulation of miR-128-3p/RAC1 in HMEC-1 cells." (PMID 35615577, 2022). "Next, we measured HULC expression in serum of sepsis patients and LPS-stimulated HUVECs, and investigated the potential mechanisms mediated by HULC in LPS-treated HUVECs." (PMID 32484206, 2020). "The recovery experiments proved that LPS induced the development of sepsis by regulating HULC/miR-204-5p/TRPM7 axis." (PMID 32484206, 2020). "Taken together, these results indicate that increase in proinflammatory ICAM1, VCAM1, and IL6 in HMECs during LPS induced sepsis in vitro is at least in part due to increase in expression of the lncRNAs HULC and UCA1." (PMID 31231228, 2019). "Coincidently, HULC could serve as a sponge for miR-204-5p, and their expression patterns were reversed in serum of sepsis patients, with HULC increase and miR-204-5p decrease." (PMID 32484206, 2020). "HULC plays an oncogene role in a variety of cancers, and a recent report revealed that increased HULC expression was related to LPS-induced inflammatory response and sepsis in endothelial cells." (PMID 32484206, 2020). "Increasing evidences demonstrate that lncRNAs are essential regulators of inflammatory response and potential biomarkers of sepsis, including NEAT1, HOTAIR, UCA1 and HULC." (PMID 36817490, 2023). "HULC and TRPM7 were increased and accompanied with decreased miR-204-5p expression in serum of sepsis patients." (PMID 32484206, 2020). "In conclusion, HULC and TRPM7 expression levels were up-regulated in sepsis patients and LPS-induced HUVECs, while miR-204-5p was down-regulated." (PMID 32484206, 2020). "The results from the current study show that along with lnc-IL17R, lncRNAs MALAT-1, HULC, and UCA1 are also upregulated during LPS induced sepsis." (PMID 31231228, 2019). "It is highly possible that there are other targets whose expression is also modulated following induction in expression of the HULC, UCA1, and MALAT-1 lncRNAs during sepsis in endothelial cells." (PMID 31231228, 2019). "RIP and qRT-PCR analysis revealed that the lncRNAs HULC, UCA1, and MALAT-1 were significantly enriched with the CMPs after sepsis." (PMID 31231228, 2019). "Given our in vivo results it seems that targeted knockdown of HULC and UCA1 might be a viable therapeutic option for sepsis, even though long-term stability and directed organ-specific delivery will be potential problems." (PMID 31231228, 2019). "As an ion channel, TRPM7 was closely related with intracellular signaling, yet we did not explore whether HULC/miR-204-5p/TRPM7 axis affected sepsis development via regulating some signaling pathways." (PMID 32484206, 2020). "Besides, we did not investigate the role of HULC/miR-204-5p/TRPM7 axis in sepsis in vivo models." (PMID 32484206, 2020).
cholangiocarcinoma (5 papers, 2016 to 2023). A carcinoma that arises from the intrahepatic biliary tree (intrahepatic cholangiocarcinoma) or from the junction, or adjacent to the junction, of the right and left hepatic ducts (hilar cholangiocarcinoma). "In cholangiocarcinoma, oxidative stress can also upregulate the expression of lncRNA H19 and lncRNA HULC." (PMID 37686677, 2023). "A recent study shows it upregulated long non-coding RNAs H19 and HULC sponging let-7a/let-7b and miR-372/miR-373 to regulate cholangiocarcinoma cell migration and invasion." (PMID 35579449, 2022). "Our previously study reported that H19 and HULC, activated by oxidative stress, promote cell migration and invasion in cholangiocarcinoma through a ceRNA manner." (PMID 30305026, 2018).
esophageal cancer (5 papers, 2016 to 2025). A primary or metastatic malignant neoplasm involving the esophagus. "For example, it was found that the POLR2E rs3787016 C > T and HULC rs7763881 A > C genetic variants were factors in the reduced risk of esophageal cancer in the younger." (PMID 38877481, 2024). "Although HULC has been strongly implicated in the development and progression of several digestive system cancers, its role in esophageal cancer remains unclear." (PMID 40909946, 2025). "This suggests that the contribution of HULC to esophageal cancer may be limited or context-dependent, warranting further investigation." (PMID 40909946, 2025).
diffuse large B-cell lymphoma (4 papers, 2016 to 2022). "In addition, expression of lncRNAs (PEG10, LUNAR1 and HULC) is correlated with clinical poor prognosis in diffuse large B cell lymphoma (DLBCL)." (PMID 27998273, 2016). "Similarly, it has been previously revealed that HULC knockdown induced cell growth arrest and apoptosis through inhibiting CCND1 expression in diffuse large B-cell lymphoma cells." (PMID 36438902, 2022).
breast carcinoma (3 papers, 2017 to 2025). "HULC decreases miRNA 15a, which in turn increases expression of p62, a critical cancer signaling protein; both miR15a and p62 have been linked to breast cancer." (PMID 31379598, 2019). "Given the biological roles of HULC’s two known targets in breast cancer pathways, HULC may be a potentially important lncRNA for breast cancer." (PMID 31379598, 2019).
liver diseases (3 papers, 2017 to 2024). "The levels of serum HULC, MALAT1, Linc00152, PTTG3P, SPRY4-IT1, UBE2CP3, and UCA1 were significantly higher in HCC patients than in patients with benign liver diseases and healthy controls, whereas serum PTENP1 was significantly decreased in HCC patients compared with healthy participants." (PMID 32733618, 2020).
thyroid cancer (3 papers, 2018 to 2023). "HULC could activate PI3K/AKT and Wnt/β-catenin pathways activities in thyroid cancer." (PMID 34690755, 2021).
Cirrhosis (2 papers, 2017 to 2023). A chronic disorder of the liver in which liver tissue becomes scarred and is partially replaced by regenerative nodules and fibrotic tissue resulting in loss of liver function. "Another four studies revealed that the serum TGFB2/TGFB2-OT1, lnc-SPARCL1-1:2, lncRNA RABGAP1L-DT-206, MALAT1, Neat1, and HULC expression were significantly higher in patients with advanced fibrosis/cirrhosis (F = 3–4) than in those without it (F = 0–2)." (PMID 36979495, 2023).
Hepatic fibrosis (2 papers, 2020 to 2022). The presence of excessive fibrous connective tissue in the liver. "Recently, in an NAFLD rat model using HULC small interfering RNA, downregulated lncRNA HULC ameliorated liver fibrosis and hepatocyte apoptosis by inhibiting the MAPK signaling pathway." (PMID 32413995, 2020).
Hepatitis (2 papers, 2017 to 2025). Inflammation of the liver. "Although the mechanisms underlying HULC upregulation in many cancer types require elucidation, many studies have analyzed hepatitis B-related HCC." (PMID 40699747, 2025). "The expression levels of HULC and MALAT1 were shown to be significantly higher in the normal background tissue of HCC than those in the normal liver tissue of metastatic liver tumor without hepatitis (HULC: fold change 14.9, P = 1.7e-06; MALAT1: fold change 17.5, P = 1.2e-06." (PMID 29170515, 2017).
Hepatitis B (2 papers, 2018). "For example, in addition to tissues, HULC was found to be up-regulated in the plasma of HCC, colorectal patients metastasized to the liver and in hepatitis B positive patients, indicating circulating HULC as diagnostic biomarker." (PMID 30158867, 2018).
nasopharyngeal carcinoma (2 papers, 2018 to 2025). A carcinoma arising from the nasopharyngeal epithelium. "In nasopharyngeal carcinoma (NPC), clinical studies have shown that HULC is highly expressed in tumor tissues and is associated with poor patient prognosis." (PMID 40909946, 2025).
benign ovarian tumors (1 paper, 2017). "In this study, HULC expression was examined in EOC, borderline and benign ovarian tumors, and normal ovarian tissues by RT-PCR." (PMID 29022892, 2017).
chronic myeloid leukemia (1 paper, 2022). "Of note, in chronic myeloid leukemia (CML), it was reported that lncRNA HULC dysregulates the miR-150-5p/MCL-1 axis to impact imatinib resistance." (PMID 35455947, 2022).
embryonal carcinoma (1 paper, 2016). A non-seminomatous malignant germ cell tumor characterized by the presence of large germ cells with abundant cytoplasm resembling epithelial cells, geographic necrosis, high mitotic activity, and pseudoglandular and pseudopapillary structures formation. "Previous studies showed that both H19 and HULC are similar to ceRNAs in human embryonic kidney cells and human embryonal carcinoma cells by sponging let-7 and miR-372, respectively." (PMID 27809873, 2016).
glioblastoma (1 paper, 2022). The most malignant astrocytic tumor (WHO grade IV). "One previous study showed that the Terpenoid backbone biosynthesis pathway was down‐regulated in glioblastoma cells due to the knock‐down of lncRNA HULC, which was involved in cell proliferation." (PMID 35044082, 2022).
lung adenocarcinoma (1 paper, 2024). A carcinoma that arises from the lung and is characterized by the presence of malignant glandular epithelial cells. "The results elucidated that 7SK and HULC could have a relationship with non-small-cell lung cancer (NSCLC) and lung adenocarcinoma (LUAD), respectively." (PMID 38495672, 2024).
melanoma (1 paper, 2013). A malignant, usually aggressive tumor composed of atypical, neoplastic melanocytes. "Hence, in this study, we selected 6 well-documented lncRNAs associated with metastasis including MALAT1, HOTAIR, NEAT-1, HULC, MEG-3, and UCA1 to evaluate their expression in primary melanoma and matched lymph node metastasis tissues." (PMID 23862139, 2013).
metastatic disease (1 paper, 2016). "In our work, we evaluated the expression of HULC, which is a lncRNA that is associated with the metastatic processes of tumors in OS pediatric primary samples from patients without metastatic disease at diagnosis." (PMID 27253450, 2016).
oral cancers (1 paper, 2019). "In this study, we found that HULC expression was considerably higher in oral cancers than in adjacent normal tissues in patients." (PMID 30677230, 2019). "Collectively, our findings reveal a crucial role of the lncRNA HULC in regulating oral cancer carcinogenesis and tumour progression, and thus suggest that HULC could serve as a novel therapeutic target for OSCC." (PMID 30677230, 2019). "We report that HULC was abnormally up‐regulated in oral cancer tissues and OSCC cell lines, and that suppression of HULC expression in OSCC cells not only inhibited the proliferation, drug tolerance, migration and invasion of the cancer cells, but also increased their apoptosis rate." (PMID 30677230, 2019). "To investigate HULC function in OSCC development, we quantified HULC expression levels in oral cancer tissues and adjacent normal tissues by using qRT‐PCR." (PMID 30677230, 2019).
pancreatic ductal adenocarcinoma (1 paper, 2025). An infiltrating adenocarcinoma that arises from the epithelial cells of the pancreas. "Complementary in vitro studies further showed that silencing HULC reduced pancreatic ductal adenocarcinoma cell proliferation, viability, invasion, and migration." (PMID 40909946, 2025). "Mechanistically, HULC appears to promote pancreatic ductal adenocarcinoma progression via multiple pathways." (PMID 40909946, 2025). "Additionally, HULC may facilitate pancreatic ductal adenocarcinoma cell proliferation and invasion through the Wnt/β-catenin signaling pathway." (PMID 40909946, 2025).